FOXC1 (forkhead box C1)
Diseases named in the same sentence as FOXC1 in open-access papers (continued):
Sharing a sentence is not in itself a finding about the gene and the disease.
glioma (9 papers, 2017 to 2025). A benign or malignant brain and spinal cord tumor that arises from glial cells (astrocytes, oligodendrocytes, ependymal cells). "The work of Pan et al29 suggests that knocking down USP34 in gliomas increases the level of FOXC1 ubiquitination and decreases its protein expression level." (PMID 40260316, 2025). "Knockdown of XIST upregulates miR-137, enhancing BTB permeability and decreasing angiogenesis in glioma via inhibition of the transcription factors forkhead box C1 (FOXC1) and ZO-2." (PMID 33980320, 2021). "XIST knockdown increased BTB permeability and inhibited glioma angiogenesis by inhibiting FOXC1 and ZO-2 expression through upregulation of miR-137." (PMID 28287613, 2017). "To elucidate the mechanism of action of miR-137 on BTB permeability and glioma angiogenesis, we confirmed that FOXC1 is a target of miR-137." (PMID 28287613, 2017). "In contrast to XIST, miR-137 was downregulated in GECs, and miR-137 overexpression contributed to the increase in BTB permeability and inhibition of glioma angiogenesis by attenuating FOXC1 and ZO-2 expression." (PMID 28287613, 2017). "In addition, higher expression of OGT, FOXC1, ASNS, GPT2, CBS, or FTH1 was also associated with poorer outcomes in clinical cases with renal clear cell carcinoma or glioma." (PMID 40416363, 2025). "High levels of FoxC1 expression have been found in gliomas and FoxC1 may regulate epithelial-to-mesenchymal transition (EMT) via Wnt/β-catenin signaling." (PMID 35456975, 2022). "Interestingly, through sponging miR-137, XIST regulates glioma angiogenesis by regulating FOXC1 (forkhead box C1) expression." (PMID 33995499, 2021). "In turn, FOXC1 decreases BTB permeability by enhancing the promoter activity and expression of ZO-1 and occludin and, as a consequence, promotes glioma angiogenesis." (PMID 32977537, 2020). "The present study investigated the expression of XIST, miR-137 and FOXC1 in GECs, and their role in BTB permeability and glioma angiogenesis." (PMID 28287613, 2017). "In the present study, we found that FOXC1 upregulation promoted CXCR7 expression by activating the CXCR7 promoter, indicating that CXCR7 is involved in FOXC1-regulated glioma angiogenesis." (PMID 28287613, 2017). "After checking the presumed targets of miR-137, FOXC1 was selected to investigate the precise mechanism of action of miR-137 on BTB permeability and glioma angiogenesis." (PMID 28287613, 2017). "FOXC1 decreased BTB permeability by increasing the promoter activity and expression of ZO-1 and occludin, and promoted glioma angiogenesis by increasing the promoter activity and expression of chemokine (C–X–C motif) receptor 7b (CXCR7)." (PMID 28287613, 2017). "We next constructed GECs with either FOXC1 overexpression or knockdown to investigate whether FOXC1 regulates BTB permeability and glioma angiogenesis." (PMID 28287613, 2017). "Moreover, FOXC1 presented a negative expression pattern with miR-137 in GECs, which promoted ZO-1 and occludin expression, led to an increase in BTB permeability, and promoted CXCR7 expression that activated glioma angiogenesis." (PMID 28287613, 2017).
pancreatic cancer (9 papers, 2015 to 2022). "In pancreatic cancer, it has been found that a high level of FOXC1 expression is strongly associated a with poor clinic outcome in patients with ductal adenocarcinomas." (PMID 25875420, 2015). "In case of pancreatic cancer, a high expression level of FOXC1 has been found to be strongly associated with the occurrence of ductal adenocarcinomas, but its exact role in pancreatic cancer development is still largely unknown." (PMID 25875420, 2015). "Overexpression of FOXC1 in MIA PaCa-2 Pancreatic Cancer cells resulted in increasing the active forms of AKT, PI3K, ERK, and p70s6k." (PMID 34540690, 2021). "IGF-1R and FOXC1 regulate each other in pancreatic cancer and FOXC1 is a direct downstream signaling molecule of IGF-1/IGF-1R axis." (PMID 34540690, 2021). "With regard to pancreatic cancer, there is a single report investigating the potential prognostic relevance of FOXC1 expression in pancreatic cancer." (PMID 34540690, 2021). "FOXC1 plays an important role in the development of pancreatic cancer as it promotes metastasis by enhancing cell proliferation, migration, invasion, epithelial-mesenchymal transition, and angiogenesis." (PMID 34957298, 2021). "In pancreatic cancer cells, miR-138-5p is suggested to play an important role in the regulation of cell growth by acting on FOXC1." (PMID 32678044, 2020). "Most recently, FOXC1 was identified as a downstream mediator of insulin-like growth factor 1 receptor (IGF1R) signaling in pancreatic cancer, where it promotes EMT and metastasis in vivo." (PMID 30764547, 2019). "Immunoblot data showed that there was a range of expression of FOXC1 among the pancreatic cancer cell lines with HPAC having high expression and MIA PaCa-2 having low expression." (PMID 29976975, 2018). "Matrigel-coated Boyden chambers were used to evaluate and examine the impact of FOXC1 on invasive capabilities of pancreatic cancer cells." (PMID 29976975, 2018). "Overall, our in vitro and in vivo data demonstrates that FOXC1 has a significant role in pancreatic cancer by increasing cell proliferation, migration, invasiveness, and metastatic capabilities." (PMID 29976975, 2018). "Overall, these results indicate that FOXC1 suppression inhibits pancreatic cancer growth and progression." (PMID 29976975, 2018). "The significant reduction in the size and number of colonies formed in response to FOXC1 silencing demonstrates that FOXC1 effectively promotes metastasis of pancreatic cancers." (PMID 29976975, 2018). "Based on our findings, we propose that FOXC1 can be used as a novel and potential therapeutic target for pancreatic cancer." (PMID 29976975, 2018). "Immunohistochemical analyses of the pancreatic cancer tissue microarray confirmed a higher expression of FOXC1 in PDACs compared with normal pancreas." (PMID 29976975, 2018). "In conclusion, FOXC1 is a potent oncogenic transcription factor, which promotes pancreatic cancer growth and metastasis." (PMID 29976975, 2018). "Screening a panel of pancreatic cancer cell lines for FOXC1 expression revealed that aggressive pancreatic cancers express higher levels compared with less aggressive pancreatic cancer cell lines." (PMID 29976975, 2018). "Both silencing and overexpression of FOXC1 exhibited the vital role of FOXC1 in pancreatic tumor growth." (PMID 29976975, 2018). "On the other hand, overexpression of FOXC1 maintained the expression levels of IGF-1R even in the presence of PPP, indicating the positive feedback regulation between IGF-1R and FOXC1, which enhances pancreatic cancer growth." (PMID 29976975, 2018). "Due to this specificity, targeting FOXC1 is expected to have less adverse side effects as a targeted therapy for pancreatic cancer patients." (PMID 29976975, 2018). "Further, FOXC1 increased the metastatic abilities of pancreatic cancer cells by enhancing cell proliferation, migration, invasion, epithelial-to-mesenchymal transition, and angiogenesis." (PMID 29976975, 2018).
pancreatic cancer (continued). "In conformity with this notion, we found that FOXC1 was down-regulated upon miR-138-5p over-expression in pancreatic cancer cells." (PMID 25875420, 2015). "A predicted target of miR-138-5p (FOXC1) was first validated using a luciferase assay and, subsequently, down-regulated by siRNA to assess its effect on pancreatic cancer cell growth." (PMID 25875420, 2015). "FOXC1 is highly expressed in breast, liver, and pancreatic cancers." (PMID 35096062, 2022). "We employed genetic approaches to overexpress and silence FOXC1 in pancreatic cancer cells." (PMID 29976975, 2018). "Hence, the present study focused to identifying the role of FOXC1 in pancreatic cancers growth and metastasis." (PMID 29976975, 2018). "Furthermore, based on intensity and quantity of the immunostaining, there was a positive correlation between the stage of pancreatic cancer progression and FOXC1 expression." (PMID 29976975, 2018). "In addition, immunohistochemical analysis of pancreatic adenocarcinomas also indicated that the expression of FOXC1 increases with advancing stages of pancreatic cancer." (PMID 29976975, 2018). "Migration, invasion, and colony formation assay data clearly demonstrate that FOXC1 is an oncogenic TF, which could be a potential therapeutic target to inhibit metastatic capabilities of pancreatic cancers." (PMID 29976975, 2018). "In the present study, we additionally show that FOXC1 may serve as a direct target of miR-138-5p in pancreatic cancer." (PMID 25875420, 2015). "Based on these observations, we hypothesized that FOXC1 might be involved in the miR-138 mediated regulation of pancreatic cancer cell growth." (PMID 25875420, 2015). "Our data indicate that miR-138-5p may play an important role in regulating pancreatic cancer cell growth, possibly through targeting FOXC1." (PMID 25875420, 2015). "We then applied siRNA to knock down FOXC1 expression in pancreatic cancer cells." (PMID 25875420, 2015). "Finally, we found that silencing of FOXC1 by siRNA had an inhibitory effect on pancreatic cancer cell growth." (PMID 25875420, 2015). "In addition, we found that exogenous over-expression of miR-138-5p inhibits pancreatic cancer cell growth, both in vitro and in vivo, and that siRNA-mediated silencing of FOXC1, a direct target of miR-138-5p, similarly inhibits pancreatic cancer cell growth." (PMID 25875420, 2015). "FOXC1 expression and promoter activity was induced in an IGF-dependent manner in pancreatic cancer cells, and occurred downstream of PI3K pathway activation." (PMID 30764547, 2019). "Thus, targeting FOXC1 could be a potential therapeutic strategy against pancreatic cancer." (PMID 29976975, 2018). "Suppression of FOXC1 decreased the levels of angiogenic markers VEGFR2 and DLL4 in pancreatic cancer cells." (PMID 29976975, 2018). "Further using a panel of seven pancreatic cancer cell lines (HPAC, Capan-2, Capan-1, AsPC-1, PANC-1, MIA PaCa-2, and BxPC-3) we analyzed the expression levels of FOXC1." (PMID 29976975, 2018). "FOXC1 silencing and overexpression studies revealed that it regulates the PI3K/AKT and ERK signaling, favoring pancreatic cancer cell growth and proliferation." (PMID 29976975, 2018). "We also found by qRT-PCR that FOXC1 is up-regulated in Capan-2 and PANC-1 cells, as well as in primary pancreatic cancer tissues, compared to normal pancreatic cells (HPDE) and nonmalignant clinical tissues, respectively." (PMID 25875420, 2015). "Furthermore, FOXC1 is not known to be actively expressed in normal cells but is highly expressed in pancreatic cancer cells, which is key for its potential to become a novel therapeutic target for pancreatic cancer." (PMID 29976975, 2018).
breast tumors (8 papers, 2010 to 2026). "However, as basal-like breast tumors generally showed a lower degree of methylation than the other subtypes, it is reasonable to expect that FOXC1 overexpression is more common in TNBC." (PMID 28493031, 2017). "Finally, to confirm that FOXC1 levels were indeed elevated in Luminal B but not HER2+ PDXs treated with GSK-126, we performed qRT-PCR on breast tumour samples at endpoint and confirmed a significant upregulation of FOXC1 transcript levels in GSK-126 treated HCI003 Luminal B but not 1991 HER2+ PDXs." (PMID 29959321, 2018). "Thus, relatively low activities of ERK, Akt, and NF-κB may contribute to low FOXC1 levels in non-basal breast tumors." (PMID 28629477, 2017).
colon cancer (7 papers, 2017 to 2024). "Three independent studies have confirmed the fact that FOXC1 expression status can in fact predict worse overall survival in colon cancer." (PMID 34540690, 2021). "Amongst the gastrointestinal cancers, the evidence in support of the prognostic utility of FOXC1 is perhaps most robust in colon cancer." (PMID 34540690, 2021). "FOXC1 also transcriptionally upregulates FGFR4 in colon cancer." (PMID 34540690, 2021). "As earlier discussed, FOXC1 transcriptionally upregulates FGFR4 in colon cancer." (PMID 34540690, 2021). "Forkhead box C1 (FOXC1) functions as a transcriptional factor to promote the transcription of miR-31-5p and downregulate LATS2, leading to oxaliplatin resistance in colon cancer cells." (PMID 36612314, 2023). "Cytolytic-high colon tumors on the other hand, were characterized by recurrent deletions at loci 1p35.3 (PIK3CD, TP73, miR34a), 6p25.3 (FOXC1), and 21q11.1 (Let-7c), and amplifications at loci 8q24.21 (MYC) and 20q13.12 (MMP9)." (PMID 31429779, 2019). "Genistein reversed the EMT of colon cancer cells by upregulation of E-cadherin and downregulation of N-cadherin, accompanied by the suppression of EMT related makers, such as Snail2/slug, ZEB1, ZEB2, FOXC1, FOXC2 and TWIST1." (PMID 29202800, 2017).
congenital heart disease (7 papers, 2016 to 2024). A heart disease that is present at birth. "Other diagnostic genetic variants, such as KMT2D and FOXC1, have been rarely reported in heterotaxy cases, although they have been verified to play roles in congenital heart disease." (PMID 35518361, 2022). "First, congenital heart defects (frequently associated with heterotaxy) are present in heterozygous patients and Foxc1 knockout mice." (PMID 33530637, 2021). "Both mutations in FOXC1 and the abnormal expression of FOXC1 significantly affect the congenital heart disease (CHD) of humans." (PMID 29552326, 2018). "Four patients with FOXC1 variants or gross deletions spanning FOXC1 had congenital heart diseases." (PMID 34745210, 2021). "Furthermore, FOXC1 was more likely to be associated with congenital heart disease, while PITX2 was always associated with dental anomalies and/or umbilical anomalies, and this is supported by previous studies." (PMID 34745210, 2021). "Human patients with FOXC1 mutations were associated with congenital heart disease." (PMID 33941187, 2021). "Despite no reported association with laterality defects, congenital heart defects are present in ARS, and these include atrial and ventricular septal defects, valve stenosis, and persistent truncus arteriosus, particularly associated with FOXC1 mutation." (PMID 33530637, 2021).
Hydrocephalus (7 papers, 2009 to 2024). Hydrocephalus is an active distension of the ventricular system of the brain resulting from inadequate passage of CSF from its point of production within the cerebral ventricles to its point of absorption into the systemic circulation. "Hydrocephalus specifically is a key phenotype of the murine Foxc1−/− mutant “congenital hydrocephalus” and an occasional finding in patients with heterozygous FOXC1 mutation or deletion." (PMID 33530637, 2021). "Animal studies have shown that mice homozygous for a null allele of Mf1 (the murine homolog of FOXC1) show congenital hydrocephalus and eye defects." (PMID 28344652, 2017). "Haploinsufficiency for FOXC1 has been associated with hydrocephalus in humans." (PMID 28344652, 2017). "Furthermore, mutations in two different genes (Foxc1 and Lmx1a) were found to be responsible for two hydrocephalus mouse models, congenital hydrocephalus (ch) and dreher (dr) mice, respectively." (PMID 19924295, 2009). "FOXC1 null mice exhibited early postnatal death with hydrocephalus, eye defects, and multiple skeletal abnormalities." (PMID 35365611, 2022). "Foxc1-mutant mice die during embryonic period due to similar defects in skeleton, oculus, and cardiovascular system, along with hydrocephalus and hypoplasia of cerebellum." (PMID 32431614, 2020). "FOXC1 knockout mice die prenatally with hydrocephalus, eye defects, and multiple skeletal abnormalities, demonstrating its critical role in the development of these tissues and organs." (PMID 27907090, 2016).
liver cancer (7 papers, 2016 to 2024). An epithelial or non-epithelial malignant neoplasm that arises from the liver. "High FOXC1 expression has been found to be associated with highly metastatic colon, breast and liver cancers." (PMID 32372224, 2020). "Overexpression of CTH significantly inhibits the proliferation, invasion, and metastasis of liver cancer cells induced by FOXC1." (PMID 39010084, 2024). "Furthermore, overexpression of FOXC1 promotes tumour metastasis and predicts poor prognosis in liver cancer." (PMID 32372224, 2020).
osteosarcoma (7 papers, 2012 to 2025). A usually aggressive malignant bone-forming mesenchymal neoplasm, predominantly affecting adolescents and young adults. "RARB has previously been identified in gene regulatory network of osteosarcoma, whereas FOXC1 (together with FOXC2) was shown to direct hypertrophic chondrocyte maturation and function toward primary ossification center formation and osteoblast recruitment." (PMID 40225119, 2025). "FOXC1 overexpression was noted on osteosarcoma cell proliferation and migration, indicating that strict control of the amount of FOXC1 in the developmental process is essential to maintain cellular homeostasis." (PMID 35365611, 2022). "FOXC1 shows high expression in osteosarcoma and promotes cancer progression and metastasis." (PMID 37754840, 2023). "In order to test whether FOXC1could regulate the expression of endogenous MSX2, we over expressed FOXC1 in U2OS human osteosarcoma cells and measured MSX2 mRNA expression by qRT-PCR." (PMID 23145080, 2012). "Thus, understanding the function of FOXC1 in normal osteoblast differentiation may help find the role of FOXC1 in osteosarcoma and osteoporosis." (PMID 37754840, 2023). "This suggests a correlation between FOXC1 and RUNX2 in osteosarcoma." (PMID 37754840, 2023).